TOPORS (TOP1 binding arginine/serine rich protein, E3 ubiquitin ligase)
Description:
Functions as an E3 ubiquitin-protein ligase and as an E3 SUMO1-protein ligase. May regulate chromatin modification through sumoylation of several chromatin modification-associated proteins. May be involved in DNA damage-induced cell death through IKBKE sumoylation.
Synonyms: p53BP3; LUN; TP53BPL; RP31
Tractability: PROTAC: UniProt records ubiquitination sites on it; ubiquitination databases record sites on it.
Gene: Protein-coding gene on chromosome 9 (32,540,544 to 32,552,603, reverse strand). Ensembl gene ENSG00000197579.
Subcellular location: Nucleus; Nucleus, PML body
Subcellular location (Human Protein Atlas): Nucleoplasm
Pathways (Reactome):
Metabolism of proteins: SUMOylation of SUMOylation proteins; SUMOylation of immune response proteins; SUMOylation of transcription cofactors
Gene Ontology:
Molecular function: antigen binding; DNA binding; DNA topoisomerase binding; protein binding; SUMO transferase activity; ubiquitin protein ligase activity; ubiquitin-protein transferase activity; metal ion binding
Biological process: DNA damage response; intrinsic apoptotic signaling pathway in response to DNA damage; maintenance of protein location in nucleus; proteasome-mediated ubiquitin-dependent protein catabolic process; protein K48-linked ubiquitination; protein localization to nucleus; protein monoubiquitination; protein polyubiquitination; protein sumoylation; ubiquitin-dependent protein catabolic process; DNA-templated transcription; negative regulation of apoptotic process; photoreceptor cell outer segment organization; retina layer formation
Cellular component: centriole; ciliary basal body; gamma-tubulin complex; nuclear speck; nucleoplasm; nucleus; photoreceptor connecting cilium; PML body; spindle pole; ubiquitin ligase complex; midbody
Genetic constraint (gnomAD): Loss-of-function variants: 25 observed, 83.51 expected, observed/expected ratio (o/e) 0.3, 90% interval 0.22 to 0.42. The upper end of that interval is the gene's LOEUF score, 0.42, which puts it in group 1 of 6, group 1 being the genes least tolerant of losing a copy. Missense variants: 1,101 observed, 1,335.7 expected, observed/expected ratio (o/e) 0.82, 90% interval 0.78 to 0.87. Synonymous variants: 473 observed, 480.17 expected, observed/expected ratio (o/e) 0.99, 90% interval 0.91 to 1.06.
Gene-disease validity (ClinGen):
ClinGen rates the evidence that TOPORS causes each of these diseases.
TOPORS-related retinopathy (autosomal dominant): Definitive. Any retinopathy caused by a variant in the TOPORS gene.
Homologues: Orthologues: chimpanzee TOPORS (99% identical), macaque TOPORS (94% identical), pig TOPORS (93% identical), rabbit TOPORS (93% identical), guinea pig TOPORS (87% identical), mouse Topors (86% identical), rat Topors (80% identical), tropical clawed frog topors (48% identical), zebrafish toporsa (31% identical), Drosophila melanogaster Topors (20% identical).
Diseases named in the same sentence as TOPORS in open-access papers:
TOPORS is named in the same sentence as 31 diseases in open-access papers, as found by Europe PMC text mining. Sharing a sentence is not in itself a finding about the gene and the disease. The quoted sentences say what the papers report.
autosomal dominant retinitis pigmentosa (6 papers, 2008 to 2024). Autosomal dominant retinitis pigmentosa (RP) is an autosomally dominant inherited retinal dystrophy leading to progressive loss of the photoreceptors and retinal pigment epithelium and resulting in blindness usually after several decades. "Mutations in TOPORS are a rare cause of autosomal dominant retinitis pigmentosa, with only a few families reported worldwide." (PMID 38592336, 2024). "TOPORS is ubiquitously expressed, yet its mutations are only known to result in autosomal dominant retinitis pigmentosa." (PMID 26872363, 2016). "Our laboratory was the first to link mutations in TOPORS with inherited autosomal dominant retinitis pigmentosa (adRP, locus RP31, MIM #609923), later shown to cause approximately 1% of all adRP." (PMID 26872363, 2016). "Heterozygous TOPORS pathogenic gene variants are associated with autosomal dominant retinitis pigmentosa, but never before with syndromic ciliopathy." (PMID 34132027, 2021). "Topoisomerase I-Binding Arginine/Serine-Rich Protein (TOPORS) may perform a variety of complex functions, and TOPORS mutations cause autosomal dominant Retinitis Pigmentosa with perivascular retinal pigment epithelium atrophy." (PMID 24244371, 2013). "The purpose of this project was to determine if mutations, including large insertions or deletions, in the recently identified RP31 gene topoisomerase I-binding arginine-serine rich (RS) protein (TOPORS), cause an appreciable fraction of autosomal dominant retinitis pigmentosa (adRP)." (PMID 18509552, 2008).
retinitis pigmentosa (5 papers, 2015 to 2024). Retinitis pigmentosa (RP) is an inherited retinal dystrophy leading to progressive loss of the photoreceptors and retinal pigment epithelium and resulting in blindness usually after several decades. "We propose that TOPORS has similar properties, with heterozygous variants causing the milder, organ‐specific ciliopathy retinitis pigmentosa, and biallelic variants causing OFDS‐spectrum syndromic ciliopathy." (PMID 34132027, 2021). "Our findings, which demonstrate a protein-protein interaction (PPI) between P26s4 and TOPORS, implicated in retinitis pigmentosa, support the involvement of P26s4 in maintenance of the retina with a potential role in retinal degeneration." (PMID 26872363, 2016). "While RNF4 loss is embryonic lethal in mice, mutations in TOPORS are associated with a variant of retinitis pigmentosa characterised by apoptotic rod cells, and with Joubert syndrome, a rare disease characterised by brain stem anomalies and in some cases retinal dystrophy." (PMID 38760575, 2024). "Furthermore, a number of other UPS proteins have been implicated in ciliopathies including TOPORS, an E3 ligase located at the basal body and cilium that is mutated in retinitis pigmentosa (RP), and TRIM32, an E3 mutated in Bardet-Biedl syndrome (BBS)." (PMID 35170427, 2022).
Alzheimer disease (2 papers, 2018 to 2020). A progressive, neurodegenerative disease characterized by loss of function and death of nerve cells in several areas of the brain leading to loss of cognitive function such as memory and language. "However, in the Alzheimer’s disease specific TMA, we only obtained significant data for TOPORS and DDIT3." (PMID 29541381, 2018).
ciliopathies (2 papers, 2021 to 2022). "Given the localization of TOPORS at the ciliary base and in the nucleus, loss of TOPORS function could cause ciliopathy‐spectrum disease by disrupting ciliary homeostasis directly or through dysregulated gene expression." (PMID 34132027, 2021).
colon cancer (2 papers, 2017 to 2019). "The cofactors PRDM1, EGR1, and TOPORS were shown to be tumor suppressors in colon cancer, leukemia, and lung cancer, respectively." (PMID 28684851, 2017).
colorectal cancer (2 papers, 2016 to 2022). A primary or metastatic malignant neoplasm that affects the colon or rectum. "Additionally, the mutational frequency was >10% in 8 other TSGs in colorectal cancer: FAT4 (19%), TOPORS (15%), PPP2CB (13%), RASL11A (13%), PCDH9 (12%), PRDM2 (12%), LIFR (11%) and TGFBR2 (11%)." (PMID 26590405, 2016). "This study reveals an alternate molecular mechanism behind LPS‐mediated tumor regression that involves TOPORS‐regulated fine‐tuning of tumor suppressor SMAR1, which dictates the ultimate fate of colorectal cancer progression." (PMID 34689394, 2022). "However, the lack of evidence for other TSGs like TOPORS in the colorectal cancer suggests that future studies are needed." (PMID 26590405, 2016).
glioma (2 papers, 2018 to 2023). A benign or malignant brain and spinal cord tumor that arises from glial cells (astrocytes, oligodendrocytes, ependymal cells). "The consultation of the Human Protein Atlas is consistent with our data where a higher expression of TOPORS was observed through immunohistochemistry analysis in 5/11 glioma specimens relative to brain tissue." (PMID 30463513, 2018). "The oncogenic effect of miRNA-21 in human glioma cells is implemented through the suppression of such tumor suppressor genes as TAp63, HNRPK, JMY, TOPORS, RECK, TP53BP2, TIMP3, PDCD4, and TGFBR2/3." (PMID 37033545, 2023).
retinal degeneration (2 papers, 2016 to 2024). Degeneration of the retina. "Given the rare nature of TOPORS-related RP, genotype–phenotype correlations of TOPORS mutations and the exact molecular mechanisms behind retinal degeneration caused by TOPORS dysfunction are still not fully understood." (PMID 38592336, 2024). "The goal of this study was to identify candidate interacting partners of TOPORS from human retina in order to delineate the mechanism of retinal degeneration associated with mutations in this ubiquitously expressed gene." (PMID 26872363, 2016). "These phenotypes are of special interest since TOPORS is a ubiquitously expressed gene, yet its mutations have been known to result only in retinal degeneration with no other symptoms." (PMID 26872363, 2016).
retinal disease (2 papers, 2008 to 2024). "In this study, we identified 7 patients from 3 families with TOPORS mutations in a cohort of 416 patients with inherited retinal disease from rural Appalachia treated at our institution." (PMID 38592336, 2024). "In this case, we report the prevalence and characterization of TOPORS mutations in a cohort of patients with inherited retinal disease from rural Appalachia." (PMID 38592336, 2024). "Given that haploinsufficiency is a likely disease mechanism for TOPORS mutations, it is possible that a gross deletion or CNV of TOPORS would also lead to retinal disease." (PMID 18509552, 2008).
colon adenocarcinoma (1 paper, 2021). "TOPORS is highly expressed in normal human colon tissues, while TOPORS mRNA and protein levels are decreased in colon adenocarcinomas relative to normal colon, probably caused by increased methylation of a CpG island in the TOPORS promoter." (PMID 33670160, 2021).
Coronary Artery Disease (1 paper, 2025). "For Coronary Artery Disease (CAD), five genes intersected between RFE and DEA analyses: CSNK1A1, AKAP5, TOPORS, ACTBL2, and FNTA." (PMID 40287491, 2025).
dementia (1 paper, 2018). Loss of intellectual abilities interfering with an individual's social and occupational functions. "We identified altered proteins in AD not common to other dementias like the E3 ubiquitin-protein ligase TOPORS, Layilin and MICB, and validated the association to AD of the previously controverted proteins DDIT3 and the E3 ubiquitin-protein ligase XIAP." (PMID 29541381, 2018).
glioblastoma (1 paper, 2016). The most malignant astrocytic tumor (WHO grade IV).
macular edema (1 paper, 2024). "Two patients were found to have novel truncating mutations in the TOPORS gene resulting in profound night blindness and visual field loss, recurrent macular edema, and in one individual, epiretinal membrane formation leading to a macular hole which was able to be successfully repaired." (PMID 38592336, 2024).
Usher syndrome type 2C (1 paper, 2012). "Several additional genes known to be involved in other forms of HRD were also located within these intervals, including the following: GPR98, underlying Usher syndrome type 2C; TOPORS, underlying adRP; and RGR, underlying arRP." (PMID 23233793, 2012).
tumor (10 papers, 2010 to 2025). "Furthermore, expression analyses and genetic studies have implicated TOPORS as a tumor suppressor in colon, lung, brain, and prostate malignancies." (PMID 20429939, 2010). "In accordance with other studies showing tumor suppressive function of miR-198, we show that TOPORS is upregulated and miR-198 is downregulated in a majority of OSCC tumors compared to their normal counterparts." (PMID 39697236, 2024). "As we have observed miR-198 to be a tumor suppressor miRNA, which targets TOPORS, it is interesting to study the role of TOPORS in OSCC cells." (PMID 39697236, 2024). "Our study demonstrated a novel molecular mechanism behind LPS‐mediated tumor regression that involves the transcriptional regulation of tumor suppressor SMAR1 by TOPORS, a zinc finger binding transcription factor via TLR4‐TRIF axis." (PMID 34689394, 2022). "It has been suggested that TOPORS is a tumor suppressor, and that its expression is reduced or undetectable in malignancies." (PMID 35061896, 2022). "Our finding that deficiency of Topors results in an increased rate of malignancy in mice supports previous analyses implicating TOPORS as a tumor suppressor in various human malignancies." (PMID 20429939, 2010). "TOPORS was found to be colocalizing with promyelocytic leukemia nuclear bodies, and its expression was substantially reduced in various cancers, implicating it to be a potential tumor suppressor protein." (PMID 34689394, 2022). "Some findings suggest that TOPORS may function as a tumor suppressor; its implication in gliomagenesis should be examined in future studies." (PMID 30463513, 2018). "Some findings suggest that TOPORS may function as a tumor suppressor; further studies are needed to clarify the exact clinical significance as well as the exact biological function of TOPORS expression in GBs." (PMID 30463513, 2018). "An IHC analysis of these tumor sections revealed that the tumors injected with LPS were displaying higher expression of SMAR1 and TOPORS as compared to the untreated set." (PMID 34689394, 2022). "Since we had observed an anti-proliferative role of miR-198, we hypothesized that the restoration of the expression level of the miR-198 by a synthetic miR-198 mimic could reduce the level of oncogenic TOPORS in OSCC cells, which might have an anti-tumor effect in vivo." (PMID 39697236, 2024).
cancer (5 papers, 2017 to 2024). A tumor composed of atypical neoplastic, often pleomorphic cells that invade other tissues. "The overexpression of TOPORS is associated with cancer cell death due to its involvement in G0/G1 arrest and apoptosis induction, which explains why it has diminished or undetectable expression levels in cancer cells." (PMID 28415805, 2017). "The relationship between the miR-198 and TOPORS is explored using bioinformatics analyses, qRT-PCR, dual-luciferase reporter assay, Western blotting and cancer hall marks assays." (PMID 39697236, 2024). "Expression level of TOPORS is high in human testis, but its’ expression is diminished or undetectable in different types of cancers, including colon, lung, and brain." (PMID 28415805, 2017). "It indicates that TOPORS may be a potential cancer gene deserving further experimental verification." (PMID 34504716, 2021).
inflammation (1 paper, 2022). Aberrant reaction of the microcirculation characterized by movement of fluid and leukocytes from the blood into extravascular tissues. "Notably we found TOPORS and UBR1 dysregulated in the USH1B organoids (GO:0010498); mutation of the former is a cause of autosomal dominant RP, and the latter promotes rhodopsin protein degradation in the OS via the UPS during retinal inflammation." (PMID 36240775, 2022).
TOPORS also shares sentences with these, for which no sentence is quoted: Bardet-Biedl syndrome (2 papers); osteosarcoma (2); colorectal adenoma (1); infection (1); Joubert syndrome (1); kidney failure (1); leukemia (1); lung adenocarcinoma (1); lung carcinoma (1); macular holes (1); nephronophthisis (1); night blindness (1); Retinal dystrophy (1).